PLK4 (polo like kinase 4)
Diseases named in the same sentence as PLK4 in open-access papers (continued):
Sharing a sentence is not in itself a finding about the gene and the disease.
microcephaly (12 papers, 2015 to 2024). A congenital or acquired developmental disorder in which the circumference of the head is smaller than normal for the person's age and sex. "Constitutive overexpression of high PLK4 levels in mouse brain and skin from embryogenesis onwards causes tissue degeneration resulting in microcephaly and impaired skin stratification, respectively." (PMID 39466849, 2024). "A previous study found that homozygous loss-of-function variants in PLK4 contribute to the formation of microcephaly and chorioretinopathy." (PMID 35366911, 2022). "The human orthologue of zyg-1 is PLK4; recessive truncating mutations in PLK4 are known to cause microcephaly, primordial dwarfism, and chorioretinopathy, making the identification and understanding of modifiers of this gene clinically relevant." (PMID 34773966, 2021). "ZYG-1 is a polo kinase that is important for centriole function and cell divisions, and mutations that truncate its human orthologue, PLK4, have been associated with microcephaly." (PMID 34773966, 2021). "Despite PLK4′s house-keeping functions in mitosis, the identification of PLK4 mutations in microcephaly patients has provided evidence that neural progenitors are particularly sensitive to its levels." (PMID 31035417, 2019). "Homozygous truncating mutations in PLK4 have been identified in seven affected members of a consanguineous family with autosomal recessive microcephaly, short statures, and chorioretinopathy, as well as in another two unrelated families." (PMID 31035417, 2019). "Aneuploid cells usually undergo apoptotic cell death and aneuploidy caused by overexpression of the centriole duplication protein Polo-like kinase 4 (PLK4) in mice results in microcephaly associated with premature cell death of the neural progenitors." (PMID 31832602, 2019). "As noted in the introduction section, a previous study showed that centrosome overduplication associated with PLK4 overexpression caused microcephaly by affecting cell division (i.e., by triggering multipolar cell division)." (PMID 27367050, 2016). "In other cases, such as for example when CDK5RAP2, CENPJ, and PLK4 are mutated, microcephaly seems to be the product of an increased cell death affecting both the progenitor and neuronal populations, due to mitotic delay and/or aneuploidy." (PMID 25729350, 2015). "Strikingly, most mouse models of microcephaly where the candidate genes (CDK5RAP2, CPAP, ASPM, Wdr62, and Plk4) were either completely ablated or highly overexpressed have invariably displayed apoptosis as a prominent mechanism for causing NPCs depletion and microcephaly." (PMID 32457578, 2020). "Given that mutations in the human orthologue of zyg-1, PLK4, are associated with microcephaly and chorioretinopathy, this study highlights the importance of having a thorough understanding of the effects of combinations of variants within a given gene and determining whether variants occur in phase." (PMID 34773966, 2021). "In vivo, in addition to induction of microcephaly, impaired skin stratification and perinatal lethality as previously reported for mice constitutively overexpressing PLK4 already, constitutive overexpression of STIL led to a shortened lifespan." (PMID 39466849, 2024). "In addition, centrosomal stress has been linked to aneuploidy resulting in significant brain degeneration and microcephaly in a Plk4 overexpression mouse model." (PMID 26044958, 2015). "Thus, the growth retardation phenotype may be associated with NAA15 duplication, speech delay with GRIA2 and microcephaly with PLK4 duplication." (PMID 35185781, 2022).
colon cancer (9 papers, 2015 to 2025). "The expression of PLK4 was increased in colon cancer cell lines LoVo and Hct116 cells compared with normal colon epithelial cell line ncm460 and the differences were statistically significant." (PMID 35912011, 2022). "Similarly, an earlier study showed that PLK4 expression enhanced the polarity, spreading, and invasion of colon cancer cells." (PMID 33778212, 2021). "Further analysis of human breast and colon cancer samples reveal that KLF14 protein expression is significantly decreased, whereas Plk4 expression is significantly increased, and a strong negative association exists between Plk4 and KLF14 expressions in the tumour tissues." (PMID 26439168, 2015). "Clinically, KLF14 transcription is significantly downregulated, whereas Plk4 transcription is upregulated in multiple types of cancers, and there exists an inverse correlation between KLF14 and Plk4 protein expression in human breast and colon cancers." (PMID 26439168, 2015). "Our results support a hypothesis that transgelin interacts with PARP1 and regulates the expression of downstream key genes (CALM1, MYO1F, NCKIPSD, PLK4, RAC1, WAS and WIPF1), which are mainly involved in the Rho signaling pathway in the human RKO colon cancer cells." (PMID 32774160, 2020). "Moreover, low KLF14 transcription is ubiquitously coupled with high Plk4 transcription in multiple forms of human cancers and there is a significant inverse correlation between the protein levels of KLF14 and Plk4 in human breast and colon cancers." (PMID 26439168, 2015).
osteosarcoma (9 papers, 2014 to 2025). A usually aggressive malignant bone-forming mesenchymal neoplasm, predominantly affecting adolescents and young adults. "In another study, oxygen deprivation of osteosarcoma cells was found to cause hypermethylation in the PLK4 promoter region, decreased PLK4 transcription, and reduced cell proliferation." (PMID 41488365, 2025). "It was observed that knockdown of NF-κB in human dermal fibroblasts, osteosarcoma, and HeLa cells resulted in the loss of PLK4 expression." (PMID 41488365, 2025). "Depletion of NF-κB in osteosarcoma cells reduced the PLK4 mRNA and protein levels and resulted in defects in centrosome structure." (PMID 41488365, 2025). "An in vitro study has shown that depleting PLK4 using siRNA led to a reduction in cell proliferation and decreased the number of centrioles in osteosarcoma cells." (PMID 41488365, 2025). "Polo-like kinase 4 (PLK4) belongs to the serine/threonine protein kinase family, and its deficiency inhibits cell proliferation in U2OS osteosarcoma." (PMID 36551309, 2022). "Under ERS, ATF6 is activated and binds to the PLK4 promoter to recruit C/EBPβ, thereby inhibiting apoptosis in osteosarcoma cells." (PMID 36551309, 2022). "However, additional studies are required to determine the exact role of PLK4 in the pathogenesis of osteosarcoma." (PMID 41488365, 2025). "This was attributed to NF-κB, which directly targets PLK4 and plays a crucial role in osteosarcoma cell proliferation, an important regulatory pathway which is involved in a variety of cellular processes including inflammatory and immune responses, cellular death, stress, adhesion and progression." (PMID 41488365, 2025). "A few studies have found an overexpression of PLK4 in osteosarcoma." (PMID 41488365, 2025). "Later, PLK4 overexpression was reported to facilitate PCM1 aggregation and survival of osteosarcoma cells." (PMID 41488365, 2025). "The overexpressed kinases in osteosarcoma, liposarcoma, and leiomyosarcoma are mainly serine/threonine kinases (BUB1, CKD4, HUNK, LKKK1, NEK2, PBK, PLK1, and PLK4), whereas TTK has a dual role (Tyrosine and serine/threonine kinase) and only MELK presents tyrosine phosphorylation activity." (PMID 40723917, 2025).
gastric cancer (8 papers, 2020 to 2025). A primary or metastatic malignant neoplasm involving the stomach. "Consistent with a negative regulatory role of KLF14 in relation to Plk4, overexpression of Plk4 lead to chromosomal instability in gastric cancer whereas Plk4-null mouse embryos had a remarkable increase of mitotic cells." (PMID 32548128, 2020). "The relevant study has also shown that PLK4 overexpression in gastric cancer induces centrosome amplification and chromosomal instability, and leads to inhibition of primary cilia formation." (PMID 32831016, 2020). "USP54 promotes gastric cancer progression by deubiquitinating PLK4." (PMID 38321455, 2024). "CEP120/USP54/PLK4 enhances centrosome amplification and gastric cancer advancement." (PMID 39605891, 2024). "Similarly, over half of the gastric cancer cell lines showed significantly elevated PLK4 mRNA levels." (PMID 36051696, 2022).
glioma (8 papers, 2020 to 2025). A benign or malignant brain and spinal cord tumor that arises from glial cells (astrocytes, oligodendrocytes, ependymal cells). "Another study indicated that high PLK4 expression is associated with unfavorable survival in glioma patients." (PMID 38326803, 2024). "The results of this study showed that gliomas with low expression of PLK4 had a higher number of IDH1 mutations (46%) as compared to those with high expression of PLK4 (22%)." (PMID 36620611, 2022). "CGGA and TCGA database analyses showed that PLK4 expression levels were positively associated with glioma grades II, III, and IV." (PMID 36620611, 2022). "In vitro and in vivo experiments confirmed that PLK4 functioned as an oncogene and was associated with M1 macrophage infiltrations in gliomas." (PMID 36620611, 2022). "The expression levels of PLK4 in glioma tissues revealed distinct somatic mutations and copy number variations." (PMID 36620611, 2022). "A high level of PLK4 expression in the TCGA dataset was associated with shorter disease-specific survival (DSS) among pan-glioma and LGG patients, as well as shorter progression-free survival (PFS) among these patients." (PMID 36620611, 2022). "Yet, PI3K/AKT and PLK4 associations have also been studied in glioma and multiple myeloma models." (PMID 40940791, 2025). "The TCGA glioma dataset was then analyzed to determine whether PLK4 expression is associated with somatic mutations and copy number variations (CNVs)." (PMID 36620611, 2022). "Based on these findings, it is suggested that mutations in the PLK4 gene may be involved in the induction of genomic instability and the progression and growth of various tumors, particularly gliomas." (PMID 36620611, 2022). "PLK4 knockout in glioma cells was shown to be correlated with differential regulation of focal adhesion pathway, MAPK signaling pathway, and PI3K/Akt signaling in a study by Wang and colleagues." (PMID 41488365, 2025). "A strong positive correlation was found between PLK4 expression and EphA2 phosphorylation in glioma tissues." (PMID 40940791, 2025). "Recently, it was observed that PLK4 can significantly enhance EphA2 signal transduction and accelerate malignant transformation and vasculogenic mimicry in glioma cells." (PMID 41488365, 2025). "TGGA and CGGA datasets for patients with gliomas indicated a correlation between PLK4 expression and prognosis." (PMID 36620611, 2022). "Totally, our study suggested that PLK4 initiates crosstalk between cell cycle, cell proliferation and M1 macrophage infiltration, contributing to malignant progression in gliomas." (PMID 36620611, 2022). "The results of flow cytometry, CCK8 and EdU assays showed that PLK4 can accelerate cell cycle and promote cell proliferation in glioma cell lines." (PMID 36620611, 2022). "Propidium iodide staining was used to detect the effect of PLK4 knockdown on the DNA content of glioma cells by flow cytometry." (PMID 36620611, 2022). "Overall, our analysis showed that PLK4 was a prognostic biomarker in pan-cancers and accounted for unfavorable survival outcomes in gliomas." (PMID 36620611, 2022). "TCGA and CGGA datasets were employed for further validation of the correlation between PLK4 mRNA expression and glioma grades or prognosis." (PMID 36620611, 2022). "We have previously explored the function of PLK4 in sensitizing chemotherapy in glioma, but there are few studies on the correlation between PLK4 and tumor immune microenvironment." (PMID 36620611, 2022). "Both in the CGGA_325, CGGA_693, and TCGA datasets, patients with PLK4-high glioma had worse prognoses than those with PLK4-low glioma." (PMID 36620611, 2022).
glioma (continued). "A poor prognosis was observed in PLK4-high glioma patients compared to those in PLK4-low glioma patients in CGGA_325 and CGGA_693 datasets, both of which were treated with chemoradiotherapy and non-chemoradiotherapy." (PMID 36620611, 2022). "Totally, despite the fact that the expression levels of PLK4 in gliomas and other cancer types varied, we found that they modulated infiltration of immune cells, and the tumor immune microenvironment in general." (PMID 36620611, 2022). "PLK4 was found to be highly expressed in various types of cancers, including glioma and closely related to histological and genetic features in public databases." (PMID 36620611, 2022). "In vitro experiments such as flow cytometry, CCK8 and EdU also confirmed that aberrant expression of PLK4 potentiates glioma by disordering the cell cycle." (PMID 36620611, 2022). "Using TCGA, CGGA, and GEO databases, we comprehensively investigated the functional role of PLK4 in multiple tumors, especially gliomas." (PMID 36620611, 2022). "There is a correlation between PLK4 expression in gliomas and tumor grades, subtypes, and new WHO types of gliomas (IDH mutation +1p19q codel, IDH mutation +1p19q non-codel, and IDH wild type)." (PMID 36620611, 2022). "According to the results of qRT-PCR, PLK4 exhibited a high expression level in glioma tissues and cell lines." (PMID 36620611, 2022). "We found that bortezomib treatment inhibited the proliferation of the glioma cells, and down‐regulation of PLK4 further enhanced this effect." (PMID 32126150, 2020). "The down‐regulation of Bcl‐2 and up‐regulation of Bax following bortezomib treatment indicate that the apoptotic process was activated in the treated glioma cells, thus mediating an anti‐tumour effect, and inhibition of PLK4 further enhanced this effect." (PMID 32126150, 2020). "PLK4 expression positively correlates with AKT1 phosphorylation in glioma tissues." (PMID 40940791, 2025). "Additionally, this group also demonstrated that PLK4 was involved in governing metabolic processes by activating PI3K/Akt/mTOR pathway in glioma cells." (PMID 41488365, 2025). "They identified Akt1 as a substrate of PLK4, which promoted glioma cell proliferation and invasion." (PMID 41488365, 2025). "A previous study by our group demonstrated that PLK4 could enhance the sensitivity to chemotherapy in gliomas by phosphorylating the inhibitor of nuclear factor-kappa B kinase subunit epsilon (IKBKE)." (PMID 36620611, 2022). "And in glioma, PLK4 mRNA were correlated with the grades and worse prognosis subtypes." (PMID 36620611, 2022). "Multiple types of cancer, including gliomas, showed increased levels of PLK4 mRNA and protein." (PMID 36620611, 2022). "Together, these results proved that PLK4 was highly expressed in glioma." (PMID 36620611, 2022). "In summary, our results demonstrated the correlation between high PLK4 expression level and malignant progression of gliomas, and the possible involvement of PLK4 in regulation of cell cycle, cell proliferation and macrophages infiltration in gliomas." (PMID 36620611, 2022). "High PLK4 expression was associated with clinical characteristic such as IDH wildtype status, 1p/19q non-codeleted status, and demethylation of MGMT, all of which were correlated with poor prognosis in patients with glioma." (PMID 36620611, 2022). "Therefore, PLK4 potentially regulates tumor immune microenvironment, cell cycle progression, and genome instability in multiple cancers, especially glioma." (PMID 36620611, 2022). "The results of the Cox regression analysis indicated that PLK4 could serve as an independent prognostic indicator in patients with gliomas." (PMID 36620611, 2022). "PLK4 was identified as overexpressed kinase in multiple malignancy, such as high‐grade glioma." (PMID 34080290, 2021). "Inhibition of PLK4 enhanced the effect of bortezomib in glioma cells." (PMID 32126150, 2020).
glioma (continued). "Furthermore, inhibition of PLK4 enhanced the effect of bortezomib in glioma cells, while overexpression of PLK4 reduced this effect." (PMID 32126150, 2020). "These phenomena could be enhanced by knockdown of PLK4, and therefore, inhibition of PLK4 might be an effective therapeutic strategy for glioma." (PMID 32126150, 2020). "Thus, PLK4 promotes the malignant phenotype of glioma by regulating cell cycle and cell proliferation, providing a new idea for us to explore novel therapeutic targets for glioma." (PMID 36620611, 2022). "Therefore, PLK4 might serve as a promising biomarker in predicting immunotherapeutic responses, sparking new hope for patients suffering glioma." (PMID 36620611, 2022). "Furthermore, the ROC curve demonstrated that PLK4 could be useful in predicting the prognosis of pan-glioma based on the CGGA_325, CGGA_693, and TCGA datasets." (PMID 36620611, 2022). "Meanwhile, PLK4 might serve as a vulnerability that can be targeted to overcome gliomas." (PMID 36620611, 2022). "Additionally, patients with glioma who expressed high levels of PLK4 had a poorer prognosis." (PMID 36620611, 2022). "Next, we analyzed PLK4 expression levels in different WHO grades, subtypes, and new types of gliomas." (PMID 36620611, 2022). "We collected protein and RNA samples from multiple glioma cell lines (U87, LN229, U251MG, A172, and T98) and human astrocyte (HA), and examined the mRNA and protein levels of PLK4." (PMID 36620611, 2022). "Compared with HA cells, the glioma cell lines had significantly higher mRNA and protein levels of PLK4; among the glioma lines, U87 and LN229 had the highest expression levels of PLK4 mRNA and protein." (PMID 36620611, 2022). "As shown in the TCGA, CGGA_693, and CGGA_325 datasets, patients with pan-glioma and LGG had shorter overall survival when PLK4 expression levels were high." (PMID 36620611, 2022). "Thus, we speculated that depletion of PLK4 could enhance the effect of bortezomib on glioma cells." (PMID 32126150, 2020). "Only in 1p19q non-codeletion glioma patients in the CGGA_325, CGGA_693, and TCGA datasets in the PLK4-high group have a worse prognosis than those in the PLK4-low group." (PMID 36620611, 2022). "To determine whether PLK4 was involved in glioma progression, we decreased PLK4 expression in U87 and LN229 cells by transfecting the cells with two siRNAs (si-PLK4#1 and si-PLK4#2)." (PMID 36620611, 2022). "And in order to verify these effects were not induced by PLK4 depletion or overexpression alone, we performed the key experiments on glioma cells without bortezomib treatment and found that there were no significantly changes in all experimental groups." (PMID 32126150, 2020).